GMFG (glia maturation factor gamma)
Synonyms: GMF-gamma
Tractability: Antibody: its Gene Ontology location is reachable by antibodies, with high confidence. PROTAC: ubiquitination databases record sites on it; its protein half-life has been measured.
Gene: Protein-coding gene on chromosome 19 (39,328,353 to 39,342,372, reverse strand). Ensembl gene ENSG00000130755.
Subcellular location (Human Protein Atlas): Cytosol; Nucleoplasm; Nuclear bodies
Pathways (Reactome):
Immune System: Neutrophil degranulation
Gene Ontology:
Molecular function: Arp2/3 complex binding; enzyme activator activity; protein kinase inhibitor activity; actin binding
Biological process: actin filament debranching; negative regulation of Arp2/3 complex-mediated actin nucleation; protein phosphorylation
Cellular component: cortical actin cytoskeleton; extracellular region; ficolin-1-rich granule lumen; secretory granule lumen
Genetic constraint (gnomAD): Loss-of-function variants: 6 observed, 8.51 expected, observed/expected ratio (o/e) 0.7, 90% interval 0.38 to 1.38. That is too few expected variants to judge how well the gene tolerates losing a copy. Missense variants: 76 observed, 83.47 expected, observed/expected ratio (o/e) 0.91, 90% interval 0.76 to 1.1. Synonymous variants: 35 observed, 29.54 expected, observed/expected ratio (o/e) 1.18, 90% interval 0.9 to 1.57.
Homologues: Orthologues: macaque GMFG (99% identical), dog GMFG (97% identical), guinea pig GMFG (96% identical), mouse Gmfg (94% identical), rat Gmfg (92% identical), chimpanzee GMFG (90% identical), tropical clawed frog gmfg (84% identical), pig GMFG (83% identical), Drosophila melanogaster GMF (51% identical), Caenorhabditis elegans Y50D7A.10 (39% identical). Paralogues in human: GMFB (82% identical).
Diseases named in the same sentence as GMFG in open-access papers:
GMFG is named in the same sentence as 51 diseases in open-access papers, as found by Europe PMC text mining. Sharing a sentence is not in itself a finding about the gene and the disease. The quoted sentences say what the papers report.
breast carcinoma (8 papers, 2021 to 2024). "RNF144A targets YY1 for proteasomal degradation to decrease the production of GMFG, hence acting as a tumor suppressor in breast cancer." (PMID 38313020, 2024). "In this study, we assessed the GMFG expression and prognosis of patients using TCGA, and we also evaluated the expression of GMFG in breast cancer subtypes." (PMID 37372337, 2023). "RNF144A exerts a negative regulatory effect on the expression of GMFG in breast cancer by specifically targeting YY1-degrading proteasomes, thereby preventing the proliferation, migration, and invasion of breast cancer cells." (PMID 38259686, 2023). "GMFG expression was tested on breast cancer cell lines including three basal-like (BT-549, MDA-MB-231, MDA-MB-436), two luminal-like (MCF-7, ZR-75B), and one Her-2 (MDA-MB-435)." (PMID 37372337, 2023). "Since breast cancer is the most commonly diagnosed malignant tumor, we further explored the expression pattern of GMFG in breast cancer, specifically." (PMID 37372337, 2023). "Further investigation revealed that GMFG was specifically increased in MDA-MB-231 compared to other breast cancer cell lines, the same as in the GEO database." (PMID 37372337, 2023). "Despite these advances, the biological function and related regulatory mechanism of GMFG in breast cancer are unclear." (PMID 35103856, 2022). "Collectively, these results suggest that RNF144A suppresses breast cancer cell proliferation, migration, and invasion through, at least in part, regulating GMFG expression." (PMID 35103856, 2022). "Eventually, functional rescue assays demonstrated that the inhibitory effects of RNF144A on breast cancer cell proliferation, migration, and invasion was reversed by re-expression of GMFG in RNF144A-overexpressing cells." (PMID 35103856, 2022). "In this study, we found that YY1 transcriptionally activates GMFG expression, and RNF144A interacts with YY1 and promotes its degradation through the ubiquitin–proteasome pathway, thus blocking YY1-mediated induction of GMFG expression in breast cancer cells." (PMID 35103856, 2022). "We further demonstrated that RNF144A suppresses breast cancer cell growth, migration, and invasion through, at least in part, negatively regulating GMFG expression." (PMID 35103856, 2022). "In order to explore the function of GMFG in tumor immunity, we analyzed the immune-related signaling pathways using GSEA, and the correlation and difference of TIICs infiltration between breast cancer (BC) tumor samples with low or high GMFG expression group." (PMID 34367945, 2021). "We found the expression of GMFG was lower in breast cancer tissues compared with normal breast tissues, which was further verified by immunohistochemical (IHC)." (PMID 34367945, 2021). "Accordingly, GMFG has the potential to become a novel biomarker for the diagnosis and treatment of breast cancer." (PMID 34367945, 2021). "And the expression of GMFG in breast cancer patients older than 60 years old is significantly higher than that in breast cancer patients younger than 60 years old (p=0.011)." (PMID 34367945, 2021). "The results suggested that GMFG expression level was correlative to sensitivity of some breast cancer chemotherapy drugs." (PMID 34367945, 2021). "Accordingly, GMFG has the potential to become a novel immune biomarker for the diagnosis and treatment of breast cancer." (PMID 34367945, 2021). "In the present study, we screened out the immune-related gene glia maturation factor γ (GMFG) that was down-regulated in breast cancer through the WGCNA analysis and differential analysis of cancer tissues and adjacent tissues." (PMID 34367945, 2021). "Moreover, GMFG exerts an antitumor role in breast cancer and is considered as a promising biomarker for the diagnosis and prognosis." (PMID 36941990, 2023). "We used bc-GenExMiner datasets to assess whether GMFG expression is correlated with breast cancer patients’ clinicopathological parameters." (PMID 37372337, 2023).
breast carcinoma (continued). "CCK8 and colony formation assays revealed that ectopic expression of RNF144A in MDA-MB-231 and Hs578T cells suppressed breast cancer cell proliferation and colony formation, but the noted effects were partially rescued following re-expression of GMFG in RNF144A overexpressing cells." (PMID 35103856, 2022). "Functional rescue assays showed that ectopic expression of RNF144A suppressed the proliferative, migratory, and invasive potential of breast cancer cells, and the noted effects were partially restored by re-expression of GMFG in RNF144A-overexpressing breast cancer cells." (PMID 35103856, 2022). "In conclusion, the findings presented in this study suggest that RNF144A exerts tumor suppressor functions in breast cancer cells through targeting transcription factor YY1 for proteasomal degradation, thus blocking YY1-mediated transcriptional activation of GMFG expression in breast cancer cells." (PMID 35103856, 2022). "To address whether RNF144A acts as a tumor suppressor in breast cancer through regulating GMFG expression, we re-expressed GMFG in MDA-MB-231 and Hs578T cells stably expressing RNF144A." (PMID 35103856, 2022). "In addition, we also found that GMFG expression level was correlated with sensitivity of some breast cancer chemotherapy drugs." (PMID 34367945, 2021). "In addition, we also found that GMFG expression level was correlative to sensitivity of some breast cancer chemotherapy drugs." (PMID 34367945, 2021). "Finally, survival analysis screened out the immune-related differential genes related to the prognosis of breast cancer, that is GMFG." (PMID 34367945, 2021). "However, the role of GMFG in breast cancer, especially in TNBC, remains unknown and demands further investigation." (PMID 37372337, 2023). "Therefore, GMFG might plays a vital antitumor effect in affecting the infiltration of immune cell, and could be used to predict the prognosis of breast cancer patients." (PMID 34367945, 2021). "Consistent with the result of TIMER, the GMFG expression in breast cancer were downregulated compared within normal breast tissue, and the pairing analysis between tumor-adjacent normal tissues and breast cancer tissues from the same patient also confirmed similar result." (PMID 34367945, 2021). "However, the role of GMFG in the occurrence and progression of breast cancer and its potential function in tumor immunology is largely unknown." (PMID 34367945, 2021). "The mRNA expression showed that all five genes were differentially expressed in breast cancer: C3, GFPT, and GMFG were significantly down-regulated, while CD27 and HLA-DPB1 were significantly up-regulated." (PMID 37287069, 2023). "However, the mechanism of abnormal GMFG expression in breast cancer cell lines remains unclear." (PMID 37372337, 2023). "To examine GMFG expression in all the subtypes of breast cancer tissues, we used IHC to detect the protein levels of GMFG in 31 Luminal A, 28 Luminal B (Her 2−), 27 Luminal B (Her 2+), 34 Her-2+, and 37 TNBC primary breast cancer tissues." (PMID 37372337, 2023). "In all cases, higher levels of GMFG were expressed in the TNBC samples but low or undetectable levels were found in the Luminal A, Luminal B (Her 2−), Luminal B (Her 2+), and Her-2+ breast cancer subtypes (p < 0.05)." (PMID 37372337, 2023). "Collectively, these findings reveal that RNF144A negatively regulates GMFG expression by targeting YY1 for proteasomal degradation, thus inhibiting the proliferation, migration, and invasion of breast cancer cells." (PMID 35103856, 2022). "Among them, CD8+ T cells had the strongest correlation with GMFG expression, which revealed that GMFG might has an antitumor effect by increasing the infiltration of CD8+ T cells in breast cancer." (PMID 34367945, 2021).
breast carcinoma (continued). "We then used machine learning methods to perform feature selection and reduction, which generated a clinical-friendly scoring system consisting of 5 genes (C3, CD27, GFPT2, GMFG, and HLA-DPB1) that could be used to predict clinical outcomes in breast cancer patients." (PMID 37287069, 2023). "Therefore, the expression of GMFG was positively correlated with the infiltration amounts of CD8+ T-cell in breast cancer, which indicated that GMFG might play an antitumor role by increasing the infiltration of CD8+ T cells in breast cancer." (PMID 34367945, 2021).
colorectal cancer (5 papers, 2020 to 2023). A primary or metastatic malignant neoplasm that affects the colon or rectum. "High expression of GMFG is associated with colorectal cancer metastasis and poor prognosis of patients with epithelial ovarian cancer, glioblastoma, lower grade glioma, lung squamous cell carcinoma, ocular melanomas, and prostate cancer." (PMID 35103856, 2022). "In addition, expression of GMFG is associated with colorectal cancer metastasis and its downregulation suppresses colorectal cancer cell migration and invasion." (PMID 35103856, 2022). "Similarly, in solid tumors such as colorectal cancer and ovarian cancer, GMFG promotes the development of cancer." (PMID 38259686, 2023). "These two studies demonstrated that GMFG could promote the migration and proliferation of ovarian and colorectal cancer cells, and the high expression of GMFG was related to poor survival outcome for ovarian cancer patients." (PMID 33863293, 2021). "Wang and colleagues first assessed GMFG expression in colorectal cancer cell lines and tissue specimens and found the targeting of GMFG expression may suppress colorectal cancer progression." (PMID 32812032, 2020). "Consequently, downregulation of GMFG suppresses colorectal cancer cell migration and invasion." (PMID 35103856, 2022).
ovarian carcinoma (5 papers, 2020 to 2023). A malignant neoplasm originating from the surface ovarian epithelium. "GMFG participates in actin reorganization, and, in ovarian cancer cells, GMFG over-expression can alter actin cytoskeleton organization." (PMID 37372337, 2023). "A previous study has shown that a high GMFG expression in epithelial ovarian cancer cells exhibits stronger migration and invasion abilities." (PMID 37372337, 2023). "Previous research has shown that expression of GMFG was able to affect invasion and migration of ovarian cancer, and was correlate with survival rate of ovarian cancer." (PMID 34367945, 2021). "GMFG protein can regulate cytoskeleton reorganization of actin in microvascular endothelial and ovarian cancer cells, which was clearly an essential factor of many cellular processes including cytokinesis, endocytosis and chemotaxis, and affected the angiogenic sprouting in zebra fish." (PMID 34367945, 2021). "Recent literature has confirmed that GMFG might contribute to the migration and invasion of ovarian cancer cells." (PMID 32528944, 2020).
lung carcinoma (4 papers, 2022 to 2024). "GMFG expression also presented statistical diagnostic values in lung cancer." (PMID 35383531, 2022). "Likewise, the higher proliferative rate was also detected in GMFG-deficient lung cancer cells relative to that in normal cancer cells." (PMID 35383531, 2022). "Hence, we also detected their expression in lung cancer cells when GMFG overexpression or deficiency." (PMID 35383531, 2022). "Conversely, GMFG deficiency promoted lung cancer growth in vitro and in vivo." (PMID 35383531, 2022). "Luciferase reporter assays were used to disclose the signaling pathway mediated by GMFG in lung cancer." (PMID 35383531, 2022). "Outcome of CCK8 assays demonstrated that overexpression of GMFG suppressed the proliferation of lung cancer cells." (PMID 35383531, 2022). "To investigate how GMFG manipulates the lung cancer progress, we carried out luciferase reporter assays to screen the potential signaling way GMFG regulates." (PMID 35383531, 2022). "In vitro loss and gain functions assays demonstrated that ectopically GMFG expression dampened the lung cancer cell proliferation while GMFG knockout escalated the cell proliferation." (PMID 35383531, 2022). "All these data suggested that GMFG promotes lung cancer cell proliferation in vitro and favors tumorgenesis in vivo." (PMID 35383531, 2022). "Our data showed that overexpression GMFG resulted in the elevated expression of P21 and Bax expression in lung cancer cells, while GMFG knockout produced an opposite results." (PMID 35383531, 2022). "Four of the five genes (HEG1, PLSCR4, GMFG, and NME4) associated with LC-BC alignments have been observed to be deregulated in lung cancer." (PMID 36101460, 2022). "To further ascertain how GMFG regulates lung cancer progression, we utilized a set of luciferase reporter vectors to screen the signaling interrupted by GMFG." (PMID 35383531, 2022). "Our findings demonstrated that GMFG was richly expressed in lung cancer based on bioinformatics analysis." (PMID 35383531, 2022). "This study disclosed that GMFG was downregualted in lung cancer tissues, and its expression was powerful in determining lung cancer prognosis and diagnosis." (PMID 35383531, 2022). "To mine the biofunction of GMFG in lung cancer, we downloaded the cohort of Lung LUSC and LUAD from TCGA database coupled with GTEx database." (PMID 35383531, 2022). "CCK8 and colony formation assays were adopted to evaluate the impact of GMFG overexpressing and depleting on lung cancer cell proliferation." (PMID 35383531, 2022). "The expression of endogenous GMFG was completely removed in lung cancer cells." (PMID 35383531, 2022). "Moreover, overexpressing GMFG constrained the lung cancer cell proliferation while depleting GMFG showed an opposite scenario." (PMID 35383531, 2022). "In our present work, we aimed to explore the role of GMFG during lung cancer progression." (PMID 35383531, 2022). "Overall, these outcome indicates that GMFG might play an important role during lung cancer malignancy." (PMID 35383531, 2022). "The expression of GMFG was evidently elevated in lung cancer cells." (PMID 35383531, 2022).
lung carcinoma (continued). "We continuously assessed GMFG depletion on lung cancer cell in vitro." (PMID 35383531, 2022). "Our outcome demonstrated that ectopic GMFG expression restrained lung cancer cell proliferation." (PMID 35383531, 2022). "Our findings suggested the essentiality of GMFG during lung cancer malignancy, and upregulating GMFG might be a promising approach for interrupting lung cancer malignancy." (PMID 35383531, 2022). "Collectively, GMFG depletion expression reduces the proliferation of lung cancer cell in vitro." (PMID 35383531, 2022). "Therefore, we further examined their expression in lung cancer cells when GMFG ectopic expression and knockout." (PMID 35383531, 2022). "Therefore, our data suggested that GMFG functions as a tumor-suppressor negatively regulating lung cancer." (PMID 35383531, 2022). "More interesting, GMFG knockout enhanced the number of cellular colony in lung cancer cell." (PMID 35383531, 2022). "The promoting effect of GMFG knockout on lung cancer tumorgenesis was also observed in vivo." (PMID 35383531, 2022). "Consequently, this study offers molecular mechanistic insight into how GMFG suppresses the lung cancer growth, proposing targeting GMFG might be a druggable approach to combat lung cancer." (PMID 35383531, 2022). "However, how GMFG regulates lung cancer progression is elusive." (PMID 35383531, 2022). "Bioinformatics analysis was employed to analyze GMFG expression in lung adenocarcinoma (LUAD) and lung squamous cancer (LUSC) as well as its significance in prognosis prediction and diagnosis in lung cancer patients." (PMID 35383531, 2022).
glioblastoma (3 papers, 2021 to 2022). The most malignant astrocytic tumor (WHO grade IV). "But, expression of GMFG in glioblastoma multiforme and kidney renal clear cell carcinoma was higher than expression in normal tissues." (PMID 34367945, 2021). "Moreover, both lower grade glioma (LGG) and glioblastoma multiforme (GBM) patients with high GMFG expression had shorter overall survival than those with low GMFG expression." (PMID 35845613, 2022).